PTH (parathyroid hormone)
Diseases named in the same sentence as PTH in open-access papers (continued):
Sharing a sentence is not in itself a finding about the gene and the disease.
Atrophy (3 papers, 2019 to 2023). Any weakening or degeneration, especially through lack of use. "We examined the cross-sectional association between thymic atrophy, evaluated as the number of CD3+CD4+CD45RA+CD31+ cells [recent thymic emigrants (RTE)/μL], and MBD-related factors [(serum PTH, FGF23, and alkaline phosphatase (ALP) level] in 125 patients with non-dialysis dependent CKD." (PMID 30692566, 2019). "In this study, it was demonstrated that thymic atrophy in CKD may be promoted by PTH." (PMID 30692566, 2019).
basal cell carcinoma (3 papers, 2021 to 2023). A carcinoma involving the basal cells.
calcinosis (3 papers, 2016 to 2025). Deposition of calcium in the tissues. "No significant abnormalities were detected in the levels of calcium, phosphorus, parathyroid hormone or vitamin D. Based on laboratory findings and the patient’s medical history, metabolic, nutritional, inflammatory and iatrogenic causes of calcinosis cutis were unlikely." (PMID 40584953, 2025).
chronic myeloid leukemia (3 papers, 2017 to 2024). "Three patients with malignancies (chronic myeloid leukemia, hepatoblastoma, and rhabdomyosarcoma) in this group had elevated PTHrP (13.3-55.1 pg/mL) and low PTH levels." (PMID 28443817, 2017).
electrolyte disorders (3 papers, 2021 to 2025). "And issues, such as serum phosphates and iron, parathyroid hormone level, renal function, hemoglobin and hematocrit, pH, inflammatory markers, and standard 12-lead ECG, were also suggested to be monitored during treatment for electrolyte disorders." (PMID 34869623, 2021).
Erythema (3 papers, 2008 to 2020). Redness of the skin, caused by hyperemia of the capillaries in the lower layers of the skin. "No skin erythema or edema was observed until 48 h after removal of PTH-loaded MNs." (PMID 30400376, 2018). "However the absence of fever and the presence of a markedly raised PTH levels along with the clinical picture of widespread necrosis with erythema made calciphylaxis a possibility." (PMID 18811973, 2008).
gallstones (3 papers, 2018 to 2023). Solid crystalline precipitates in the biliary tract, usually formed in the gallbladder, resulting in the condition of cholelithiasis. "The mechanism of PTH-associated gallstone formation may involve inhibition of gallbladder emptying, hepatic bile secretion and Oddi’s sphincter motility as well as modification of bile composition." (PMID 29301445, 2018). "Female gender, low creatinine, high phosphorus and high PTH levels might be factors increasing the formation of gallstones." (PMID 29301445, 2018). "Our baseline laboratory values such as serum corrected Ca, phosphorus, ALP, LDL-C and whole PTH levels were not significantly different between the HD patients with gallstones and those without gallstones (data not shown)." (PMID 29301445, 2018).
gestational diabetes (3 papers, 2018 to 2021). Carbohydrate intolerance first diagnosed during pregnancy. "Finally, we wanted to explore the association of total and free 25(OH)D, 1,25(OH)2D and PTH levels with pregnancy outcomes (gestational diabetes mellitus (GDM) and birthweight)." (PMID 29641551, 2018).
Headache (3 papers, 2014 to 2023). Cephalgia, or pain sensed in various parts of the head, not confined to the area of distribution of any nerve. "In the 100 PTH patients, the mean headache frequency was 25.4 ± 7.1, indicating a large headache burden in this population." (PMID 37627930, 2023). "Deep phenotyping of the post-traumatic headache population was therefore performed examining 100 patients with persistent PTH acquired after a mild TBI." (PMID 37627930, 2023). "Trial limitations include the chosen primary outcome, blinding a behavioral trial, definition of PTH as headache onset within 3 months of head injury (instead of 7 days per ICHD-3 5.2.2), and missing data/dropout." (PMID 35759281, 2022). "Results of this randomized clinical trial found that US military combat veterans with PTH attributable to mTBI and comorbid PTSD symptoms showed significant improvement in headache-related disability and PTSD symptom severity in response to nonpharmacological interventions for headache and PTSD." (PMID 35759281, 2022).
hemorrhagic stroke (3 papers, 2014 to 2023). A stroke caused by a bleed on the brain. "An intact PTH level>500 pg/mL was significantly associated with incident hemorrhagic stroke compared with an intact PTH level of 151–300 pg/mL (OR, 1.54; 95% CI, 1.10–2.17)." (PMID 25494334, 2014). "Despite the low incidence of hemorrhagic stroke in our sample and hence low statistical power, a significant association with intact PTH levels>500 pg/mL was detected." (PMID 25494334, 2014). "MI was associated with phosphate, calcium, and intact PTH levels, whereas hemorrhagic stroke was associated only with intact PTH." (PMID 25494334, 2014). "Hemorrhagic stroke was significantly associated only with a high intact PTH level." (PMID 25494334, 2014). "Hemorrhagic stroke was associated only with intact PTH levels>500 pg/mL (1.54; 1.10–2.17)." (PMID 25494334, 2014). "High intact PTH levels, but not P or cCa levels, were associated with incident hemorrhagic stroke." (PMID 25494334, 2014).
hyperprolactinemia (3 papers, 2022 to 2025). Abnormally high level of prolactin in the blood. "A previous animal study performed on 50 adult female rats found that hyperprolactinemia induced estrogen deficiency with a direct effect on the bone and caused bone loss in women, and estrogen and prolactin could increase serum 1,25(OH)2D3 and PTH levels." (PMID 36313749, 2022).
Hyponatremia (3 papers, 2022 to 2025). An abnormally decreased sodium concentration in the blood. "In a single study on hyponatremia secondary to SIADH, the levels of 1–250 H vitamin D and of PTH were reported to be normal." (PMID 36675652, 2023).
lung disease (3 papers, 2015 to 2021). "Patients who reinitiated cinacalcet treatment after a discontinuation had longer median dialysis vintage, were more likely to be female, and lower % with lung disease, but higher median PTH levels at start of discontinuation [310 (IQR: 145, 575) vs 237 (IQR: 117, 518) pg/ml]." (PMID 31088377, 2019).
lung squamous cell carcinoma (3 papers, 2017 to 2025). "We identified six hormone levels to be significantly associated with lung squamous cell carcinoma (LUSC): total testosterone, oestradiol, thyrotropin-releasing hormone, insulin, parathyroid hormone, and glucocorticoid." (PMID 40017690, 2025).
metastatic disease (3 papers, 2018 to 2025). "The differential diagnosis between parathyroid and thyroid tumours, paraganglioma, haematological or metastatic tumours can be clarified via PTH, chromogranin A, TTF-1, calcitonin, LCA, CD56 and vimentin, among others." (PMID 35805976, 2022).
multiple sclerosis (3 papers, 2012 to 2025). A progressive autoimmune disorder affecting the central nervous system resulting in demyelination. "Relapses in multiple sclerosis occur when intact PTH serum levels are > 30 %URL." (PMID 23202962, 2012). "This study did not evaluate calcium, phosphorus and the parathyroid hormone in determining the biological effect of vitamin D in patients with multiple sclerosis." (PMID 36986195, 2023).
myelofibrosis (3 papers, 2016 to 2023). A partial or complete replacement of the bone marrow stroma by fibrous tissue. "Erythrocyte lifespans decrease in response to high PTH levels; and high PTH levels inhibit hematopoietic stem cell activity, particularly that of erythroid burst-forming units, as well as inducing myelofibrosis and contributing to erythropoietin resistance." (PMID 27764168, 2016). "Thirdly, increased PTH levels can lead to myelofibrosis and cardiac fibrosis in ESRD and may mediate cardiovascular fibrosis and apoptosis through the TGF-β signaling pathway, resulting in a hyperinflammatory state." (PMID 37051200, 2023).
neutropenia (3 papers, 2015 to 2025). A decrease in the number of neutrophils found in the blood. "A 66-year-old female with a recent diagnosis of tonsillar diffuse B-cell lymphoma admitted with complaints of generalized weakness after one cycle of R-CHOP, found to have neutropenia, a low calcium level, high PTH, and low 25-hydroxy Vitamin D levels." (PMID 26858923, 2015).
non-small cell lung carcinoma (3 papers, 2021 to 2025). A group of at least three distinct histological types of lung cancer, including non-small cell squamous cell carcinoma, adenocarcinoma, and large cell carcinoma. "Joint KEGG enrichment analysis identified five pivotal pathways shared between the transcriptomic and metabolomic datasets: cAMP signaling, pathways in cancer, non-small cell lung cancer, glutamatergic synapse, and parathyroid hormone synthesis, secretion and action." (PMID 41300134, 2025).
osteosclerosis (3 papers, 2021 to 2025). Abnormally high bone density. "Although purely speculative, an inadequate normalization of serum parathyroid hormone or increase of urinary DPD in the early phase after allo-HSCT (30 days) could be indicative of a treatment failure with particularly high diagnostic value for the outcome osteosclerosis." (PMID 39833182, 2025).
pneumonia (3 papers, 2012 to 2022). An acute, acute and chronic, or chronic inflammation focally or diffusely affecting the lung parenchyma, caused by an infection in one or both of the lungs (by bacteria, viruses, fungi, or mycoplasma.). "Cardiac abnormalities have been reported in patients with high levels of PTH, which may lead to circulatory problems and even death and can also contribute to the high frequency of pneumonia." (PMID 23227372, 2012).
psoriasis (3 papers, 2022 to 2023). An autoimmune condition characterized by red, well-delineated plaques with silvery scales that are usually on the extensor surfaces and scalp. "Indeed, vitamin D has a central role in bone turnover, through the regulation of calcium and phosphate metabolism, and in the control of parathyroid hormone (PTH) secretion, thus suggesting to check not only the parameters directly associated with psoriasis but also those related to bone metabolism." (PMID 37571324, 2023). "Seven studies described serum PTH levels among 450 patients (51.9%) affected by psoriasis and 417 controls (48.1%)." (PMID 37571324, 2023). "Patients with psoriasis had higher levels of PTH than controls, with a mean difference of 5.06, CI: 1.0, 9.1 pg/mL (43.7 ± 16.5 vs. 38.7 ± 12.8, p = 0.015)." (PMID 37571324, 2023). "A possible explanation of high PTH levels can be a relationship with vitamin D metabolism, which has been found to be reduced in psoriasis in order to maintain adequate serum calcium levels." (PMID 37571324, 2023). "Furthermore, serum PTH levels were significantly higher in psoriatic patients than controls, suggesting a possible relationship with the pathogenesis of psoriasis." (PMID 37571324, 2023). "Indeed, this finding could link high PTH levels to the pathogenesis of psoriasis, in which T-helper lymphocytes 17 are involved." (PMID 37571324, 2023). "Parathyroid hormone (PTH) levels inversely decreased significantly from 57.8 ± 16.7 to 28.9 ± 8.2 pg/mL and from 55.3 ± 25.0 to 25.4 ± 10.7 pg/mL in patients with psoriasis and vitiligo, respectively." (PMID 35458137, 2022).
Salmonella Infections (3 papers, 2021 to 2023). Infections with bacteria of the genus SALMONELLA. "KEGG analysis showed that the DEGs were primarily involved in five metabolic pathways, including parathyroid hormone synthesis, secretion and action, endocrine resistance, salmonella infection, ferroptosis, and cancer signal pathways." (PMID 36768499, 2023).
Sanjad-Sakati syndrome (3 papers, 2017 to 2024). "Among the genetic disorders related to PTH, Sanjad-Sakati syndrome (SSS), also known as hypoparathyroidism-retardation-dysmorphism (HRD) syndrome, is notable." (PMID 39246904, 2024).
sarcoma (3 papers, 2020 to 2022). A usually aggressive malignant neoplasm of the soft tissue or bone. "Although in vitro and in vivo studies have demonstrated the risks of elevated parathyroid hormone with development of sarcomas, there is limited evidence of a human association." (PMID 32440625, 2020). "We therefore focussed on this connection by studying PTH action on osteoblast-rich cultures from newborn rat calvaria and on clonal rat osteogenic sarcoma cells that expressed many phenotypic features of osteoblasts." (PMID 35126319, 2021).
scleroderma (3 papers, 2013 to 2023). Scleroderma is a rare autoimmune connective tissue disorder characterized by abnormal hardening of the skin and, sometimes, other organs. "The purpose of this study was to evaluate serum Klotho, FGF-23, intact PTH (iPTH) and vitamin D levels in scleroderma patients compared with the healthy controls." (PMID 28540270, 2017). "In scleroderma group the serum levels of 25(OH)D3 significantly correlated with PTH levels, BMD, stiffness index and bone turnover markers." (PMID 23818972, 2013). "Plasma parathyroid hormone levels showed an inverse correlation with vitamin D3 levels, already reported in other papers, and can thus be interpreted as a response correlated with the lower levels of vitamin D3 observed in our patients affected by scleroderma." (PMID 23818972, 2013).
Splenomegaly (3 papers, 2024 to 2026). Abnormal increased size of the spleen. "Patients with high ferritin levels, increased splenomegaly, short height, and low body weight and patients in the high-risk group with low Ca, P, and vitamin 25 OH D levels and high ALP and PTH levels should be followed up more frequently." (PMID 40095502, 2025).
systemic lupus erythematosus (3 papers, 2021 to 2023). An autoimmune multi-organ disease typically associated with vasculopathy and autoantibody production. "Etanercept increased serum PTH levels in the FcγRIIb-/- mouse model of lupus." (PMID 33861790, 2021).
thymoma (3 papers, 2008 to 2021). A neoplasm arising from the epithelial cells of the thymus. "Histopathology confirmed a type AB thymoma, with no parathyroid tissue identified and no PTH markers present." (PMID 31832580, 2019).
upper respiratory tract infection (3 papers, 2020 to 2024). "The most common treatment‐emergent AEs in the MAD cohorts administered TransCon PTH were headache (12%), dizziness (10%), palpitations and catheter site phlebitis (each 8%), postural dizziness and upper respiratory tract infections (each 6%), and presyncope and musculoskeletal pain (each 6%)." (PMID 32212275, 2020).
urinary tract infection (3 papers, 2018 to 2024). "Negative correlations between calcium and PTH as well as an association of vitamin D with higher risk of urinary tract infection were reported." (PMID 29973985, 2018).
vitamin B12 deficiency (3 papers, 2019 to 2024). A disease characterized by low serum levels of vitamin B12, either inherited or acquired. "Less than 10% of patients from all groups suffered from iron or calcium deficiency and 2% or less of the patients presented a vitamin A and vitamin B12 deficiency or high PTH after 2 years." (PMID 38807643, 2024).
Zinc deficiency (3 papers, 2021 to 2025). A deficiency of the essential metal Zinc; an essential cofactor for many enzymes. "Zinc deficiency is suspected to cause an increase in PTH due to its contribution in maintaining calcium homeostasis." (PMID 34631763, 2021). "It has been suggested that zinc deficiency may indirectly affect bone mineral density by reducing intestinal calcium absorption and enhance the bone resorption effects of PTH through increasing PTH levels." (PMID 37924110, 2023).
adenocarcinoma of the lung (2 papers, 2020 to 2025). "Five hormone levels were significantly associated with lung adenocarcinoma (LUAD): luteinizing hormone, thyroid hormones, insulin, prolactin levels, and parathyroid hormone." (PMID 40017690, 2025).
allergic dermatitis (2 papers, 2023 to 2025). "The parathyroid hormone pathway, which is a control of the keratinocyte differentiation and proliferation and angiogenesis of the skin, provides indirect support for the treatment of propolis on ultraviolet allergic dermatitis." (PMID 40232010, 2025). "Some of the overlapping targets between propolis and UV allergic dermatitis were enriched in the TNF signaling pathway, C-type lectin receptor signaling pathway, and parathyroid hormone synthesis, secretion, and action pathways." (PMID 40232010, 2025).
alopecia (2 papers, 2017 to 2024). Hair loss usually from the scalp. "But it is difficult to maintain normocalcemia and to suppress PTH level in patients with HVDRR, especially patients with alopecia." (PMID 27796266, 2017). "After 4 months of this combination therapy, long-term normocalcemia and PTH suppression with normalization of serum phosphorus level were achieved in addition to radiological healing, but, as expected, there was no recovery in alopecia." (PMID 27796266, 2017). "Enteral or parenteral calcium infusions are reported to suppress PTH level with metabolic and radiological healing in HVDRR patients with or without alopecia." (PMID 27796266, 2017).
amyloidosis (2 papers, 2017 to 2020). A disorder characterized by the localized or diffuse accumulation of amyloid protein in various anatomic sites. "Triglyceride, P and PTH levels were higher in patients with FMF-related amyloidosis (p < 0.001, p < 0.001 and p = 0.004, respectively)." (PMID 33110219, 2020). "In addition, even though the pathogenesis of CKD arthropathy is multi-factorial, some factors affecting abnormal bone turnover such as PTH, amyloidosis, inflammatory cytokines, and uremic toxins were not investigated." (PMID 28596576, 2017).
anorexia nervosa (2 papers, 2020 to 2021). A disorder most often seen in adolescent females characterized by a refusal to maintain a minimally normal body weight, an intense fear of gaining weight, a disturbance in body image, and, in postmenarcheal females, the development of amenorrhea. "The present pilot study investigated the effect of Teriparatide 1–34 rh-PTH (TPT) in young women diagnosed with anorexia nervosa (AN), and markedly compromised Bone Mineral Density (BMD)." (PMID 33420643, 2021).
atrioventricular block (2 papers, 2001 to 2021). A heart block that is initiated in the atrioventricular node. "Measures should be taken to normalize the parathyroid hormone, calcium, and phosphorus levels to limit the progression of atrioventricular block." (PMID 33728211, 2021).
autosomal dominant polycystic kidney disease (2 papers, 2024 to 2025). Autosomal dominant form of polycystic kidney disease. "Even in patients with autosomal dominant polycystic kidney disease (ADPKD), lower levels of alkaline phosphatase and PTH together with higher circulating intact FGF-23 (iFGF-23) and decreased bone formation rate have been demonstrated." (PMID 39684548, 2024).
beta thalassemia (2 papers, 2019 to 2024). Beta-thalassemia (BT) is characterized by deficiency (Beta+) or absence (Beta0) of synthesis of the beta globin chains of hemoglobin (Hb). "Interestingly, previous reports indicated reduced PTH levels in patients with thalassemia major and suggested that these patients would benefit from vitamin D and calcium supplementation." (PMID 31646984, 2019).
bone marrow fibrosis (2 papers, 2010 to 2022). "Excessive secretion of PTH can cause bone marrow fibrosis, inhibit endogenous erythropoietin (EPO), suppress erythroid progenitors, and reduce red blood cell survival." (PMID 36142295, 2022). "Apart from the reversal of bone marrow fibrosis and enhanced erythropoietin production, we propose that the removal of excess PTH also contributed to improvement in iron-restricted erythropoiesis." (PMID 36142295, 2022). "Mice, in turn, were resistant to the development of PTH-induced bone marrow fibrosis." (PMID 20200965, 2010).